ANXA1 (annexin A1)
Diseases named in the same sentence as ANXA1 in open-access papers (continued):
Sharing a sentence is not in itself a finding about the gene and the disease.
tumor (continued). "In summary, the absence of ANXA1 in tumor cells reduced tumor bulk formation and significantly reduced association with vascular structures, with tumor cells shifting toward a more diffusely infiltrative phenotype." (PMID 40683881, 2025). "Additionally, proteins associated with neoplasm invasiveness and metastasis (SRC, ALDOA, ACTB, MAPK1, and RAC1) and those mediating epithelial to mesenchymal transition (annexin A1, Hsp27) were upregulated in the LNM group." (PMID 41193833, 2025). "In coculture with AGS and Jurkat cell, si-PRSS22 treatment could reduce the tumor cell growth, migration, Edu positivity, and the immune evasion ability, which would be reversed by suppressing ANXA1." (PMID 41497316, 2025). "Mechanistically, ANXA1 plays roles in inflammation and tumor cell migration." (PMID 40683881, 2025). "Data from The Cancer Genome Atlas (TCGA) and the Gene Expression Omnibus (GEO) allow a comprehensive bioinformatics analysis, while the Tumor Immune Estimation Resource (TIMER) provides tools to explore the relationship between ANXA1 expression and immune cell infiltration in CRC tissues." (PMID 41283264, 2025). "This paradoxical increase suggests that while the tumor initially evades immune detection through low ANXA1 levels, under the selective pressure of immunotherapy, it may upregulate ANXA1 in immune cells to enhance its immunosuppressive environment." (PMID 40744683, 2025). "Additionally, the increased secreted form of ANXA1 is able to activate FPR by inducing the slowdown of tumor progression." (PMID 40227604, 2025). "Tumor cells may exacerbate this effect by upregulating ANXA1 and activating related signaling pathways, such as AKT, thereby establishing a negative feedback loop that impedes the efficacy of PD‐1/PD‐L1 blockade therapies." (PMID 40744683, 2025). "Addressing these suppressive influences is crucial for effective anti-tumor immunity and can be exploited in ANXA1-high tumors, where PD-1 blockade or anti-IL-10 therapies might be effective." (PMID 40361334, 2025). "ANXA1’s expression on tumor cells and macrophages, as demonstrated by IHC and double IF staining, suggests that it might facilitate a microenvironment conducive to tumor growth and resistant to immune attack." (PMID 40361334, 2025). "Additionally, standardized assays are required to implement ANXA1 serum detection in clinical practice, considering its complex dual role in tumor progression and metastasis." (PMID 41283264, 2025). "Research suggests that ANXA1 not only supports tumor growth through its effect on tumor cell metabolism but may also influence the immune microenvironment by regulating immune cell metabolism." (PMID 40390008, 2025). "We further investigated ANXA1 expression in 78 paired ICC tumor and adjacent normal tissue samples." (PMID 40390008, 2025). "The complexity of the tumor microenvironment is highlighted by single‐cell sequencing studies showing high ANXA1 expression across all immune cells in the context of PD‐1/PD‐L1 drug resistance, suggesting an adaptive response of the tumor microenvironment to ICB treatments." (PMID 40744683, 2025). "Overall, these findings strongly support the ANXA1 value as a predictive and prognostic biomarker in CRC and RC, given its association with nCRT poor response, advanced disease stages, and aggressive tumor features, with some specific functional correlations for each location." (PMID 41283264, 2025). "Under complete culture medium conditions, compared with the control group, ANXA1 knockdown cells showed significant growth, and overexpression of GOT1 could almost rescue ANXA1 knockdown tumor inhibition." (PMID 40390008, 2025). "ANXA1 is also involved in the process of tumor resistance, but whether it alleviates drug resistance or promotes drug resistance is still controversial." (PMID 39712859, 2025). "Also, in this cohort, ANXA1 expression was observed localized to tumor cells near blood vessels, both within the tumor core and outside the tumor bulk." (PMID 40683881, 2025).
tumor (continued). "The literature data suggest that ANXA1 may possess a role in tumor resistance to nCRT in LARC patients, albeit relatively limited direct investigations of an ANXA1-nCRT response have been performed." (PMID 41283264, 2025). "The authors suggest that ANXA1 may act as a tumor suppressor gene capable of modulating the proliferative function of estrogens." (PMID 38892394, 2024). "The band pattern of ANXA1 showed hardly any differences between the tumor and the control tissue." (PMID 38893148, 2024). "As a result, further studies are needed to investigate whether the inhibition of ANXA1 could provide a new therapeutic approach in certain major tumour types." (PMID 38200229, 2024). "However, more recently, a growing number of studies have suggested that ANXA1 can promote tumour development and progression." (PMID 38200229, 2024). "The function of ANXA1 may be specific to each tumor type due to post-translational modifications of the protein impacting expression across a range of cell and cancer types." (PMID 38893148, 2024). "One such explanation is based on the fact that ANXA1 can be specific to each tumor type due to post-translational modifications of the protein, which could account for the alterations in surface expression seen on different cells and in different cancers." (PMID 38892394, 2024). "The expression level and function of ANXA1 vary according to tumor type." (PMID 39447086, 2024). "There have been suggestions that the role of ANXA1 may be specific to each tumour type due to post-translational modifications of the protein impacting expression across a range of cell types or cancer indications." (PMID 38200229, 2024). "Furthermore, ANXA1 is a key component of tumour-derived extracellular vesicles promoting migration, invasion and angiogenesis and is secreted by cancer associated fibroblasts increasing cancer stem cell generation." (PMID 38200229, 2024). "Due to the heterogeneity of tumor tissue, the proportion of different cell types in the tumor lysates and therefore the extent of ANXA1 expression may vary." (PMID 38893148, 2024). "Indeed, assessing ANXA1 expression by immunohistochemistry has been shown to be complicated by a lack of available antibodies that are both specific for ANXA1 and can bind the cleaved form of ANXA1 previously identified in tumour vasculature." (PMID 38200229, 2024). "Thus, ablation of the Notch1‐p15‐mediated tumor suppression by ANXA1 provided a novel mechanism of AML proliferation." (PMID 39447086, 2024). "Our study found that ANXA1 antagonizes the anti-tumor effects of honokiol by stabilizing ROS." (PMID 36678567, 2023). "In addition to ANXA1, the ANXA proteins ANXA2, ANXA9 and ANXA10 are associated with tumour cell adhesion, invasion and metastasis." (PMID 36936694, 2023). "Previous studies showed that ANXA1 was involved in the proliferation and invasion of a variety of tumor cells, and we also found that downregulated ANXA1 promoted the proliferation of ES cells, which may lead to progression and metastasis in ES patients." (PMID 36988561, 2023). "However, the role of ANXA1 in tumors remains uncertain, both as an antitumor factor and as a promoter of tumor progression." (PMID 36988561, 2023). "This could attribute to the sample size difference and contradictory role of ANXA1 in regulating proliferation and tumor growth in cancer." (PMID 37464398, 2023). "Authors suggested that loss of Annexin-A1 is a consequence of rather than an etiological factor for tumor development." (PMID 37954869, 2023). "AnxA1 is also expressed in the tumor microenvironment, being mainly attributed to cancer cells." (PMID 36766767, 2023). "Thus, targeting feedback-expressed proteins such as ANXA1 is essential for maintaining and enhancing the anti-tumor effects of honokiol." (PMID 36678567, 2023).
tumor (continued). "In a model of human BC, ANXA1 can promote tumor-formation, and it has been suggested that some basal-like TNBCs may require high endogenous tumor cell Annexin A1 expression for continued growth." (PMID 37189694, 2023). "Recent research suggests that the role of Anxa1 in tumorigenesis is context-dependent, whereby it may act as either a tumor suppressor or a tumor promoter, depending on the specific characteristics of tumor cells or tissues involved." (PMID 37950728, 2023). "In other words, ANXA1 mediates the uptake of tumor antigens for presentation." (PMID 37705051, 2023). "Thus, our results showed that HCT116 cells with ANXA1 knockdown had a lower rate of tumor formation, and the resultant tumor grew slowly and tended to subside easily in vivo compared with parent cells." (PMID 36678567, 2023). "The expression levels of ANXA1 were negatively correlated with tumor purity (r=-0.271, P=1.64e-05), but positively correlated with the levels of infiltrating B cells (r=0.04, P=5.4e-01), CD8+ T cells (r=0.175, P=6.64e-03), CD4+ T cells (r=0.256, P=6.15e-05), macrophages (r=0." (PMID 36988561, 2023). "ANXA1 expression was found to vary, depending on tumor type, suggesting it may play a role in the regulation of tumor cell proliferation and tumor growth." (PMID 37735492, 2023). "AnxA1+ neutrophils are fundamental to halting inflammation, and although AnxA1 secreted by cancer cells is involved in metastasis development, the role of AnxA1 derived from neutrophils in tumor invasiveness is underestimated." (PMID 36766767, 2023). "Nonetheless, we may also suggest that AnxA1 secreted by N2 phenotype neutrophils influences stromal and immune cell behavior in the microenvironment, favoring the tumor progress." (PMID 36766767, 2023). "The recruitment of such antigen presenting cells into the tumor bed is orchestrated by the specific temporal and spatial appearance of ICD-associated DAMPs, including the early release of adenosine triphosphate (ATP) and annexin A1 (ANXA1)." (PMID 37907944, 2023). "Using the TISIDB database to determine which types of TILs might be regulated by ANXA1, we found that ANXA1 might affect the immune regulation of various tumours, including GBM." (PMID 35770335, 2022). "Studies have also suggested that ANXA1 may be specific to each tumour type due to post‐translational modifications of the protein." (PMID 35146757, 2022). "Interestingly, knockdown of ANXA1 both in vivo and in vitro enhanced the anti‐tumour effects of bortezomib, a commonly used treatment in multiple myeloma (MM)." (PMID 35146757, 2022). "Moreover, silencing Annexin-A1 inhibits the changes in the gut microbiome and fatty acid metabolism after stress as well as basal and stress-induced tumor growth." (PMID 35664067, 2022). "In general, the effect of ANXA1 on tumour cells seems to be diverse and sometimes even opposing due to mutations in the gene, hypermethylation of the promoter and subsequent loss of transcription, posttranslational modification of the protein, and defects in protein storage, among others." (PMID 35415239, 2022). "First of all, we could prove that the presence of ANXA1 in the WT spheroids is decisive for the creation of this tumor model reflecting the main PC features." (PMID 36230687, 2022). "There were significant differences between low and high ANXA1 expression based on age (p = 0.002), tumour location (p = 0.001), recurrence (p = 0.048), WHO grade (p = 0.005), CD1a (p = 0.015) and PD‐L1 expression (p = 0.000); however, other parameters were not correlated with this difference." (PMID 35770335, 2022). "Finally, as no tumors developed in the ANXA1-/- mice, we next determined if ANXA1 interacts with hub genes to enhance oncogenesis based on the RNA-seq and epigenetic analysis of the ANXA1+/+ tumor samples." (PMID 35664067, 2022).
tumor (continued). "This cycle also sheds light on how ANXA1 is responsible for the infiltration of microglial cells into the tumor microenvironment and subsequently provides beneficial support to the survival of cancer cells facing the rigors of invading new microenvironments, leading to a clinical worse prognosis." (PMID 35382852, 2022). "Additionally, this study has highlighted that the extracellular ANXA1 action is strengthened through the EVs supporting spheroids growth and resistance to drug treatment, mainly affecting tumor progression." (PMID 36230687, 2022). "However, studies have found that ANXA1 expression is different depending on tumour type and that ANXA1 acts as either an oncogene or a suppressor gene." (PMID 35770335, 2022). "In addition, more comprehensive and in-depth studies have found that the expression pattern and function of ANXA1 in different tumor types are tissue-specific." (PMID 34991599, 2022). "Furthermore, treatment of rats with an anti‐ANXA1 radioimmunotherapy destroyed tumours and increased survival in these animals." (PMID 35146757, 2022). "Moreover, ANXA1 was shown to be a key component of extracellular vesicles released by pancreatic cancer cells and was able to influence the tumour microenvironment by triggering mesenchymal switches and cell motility on fibroblasts and endothelial cells." (PMID 35146757, 2022). "Additionally, morphological results of the immunohistochemistry assay showed that ANXA1 upregulates with an increase in tumour grade." (PMID 35770335, 2022). "In our study, we suggest that the interaction between the AnxA1 and IL-6 signaling pathways could be involved in the establishment of a tumor-promoting microenvironment." (PMID 35626741, 2022). "In summary, our findings demonstrated that ANXA1 promoted tumor progression by activating EGFR signaling, which revealed that ANXA1 might be a prognostic predictor and underlying therapeutic target for BLCA." (PMID 34991599, 2022). "Likewise, ANXA1 can also exert a pro-tumorigenic role in HNC by regulating tumor growth and metastasis through FPR2." (PMID 36247003, 2022). "Further investigation should employ the TNBC-macrophage co-culture models to explore the AnxA1-mediated tumor-immune crosstalk, which may reveal the exciting role of AnxA1 in the tumor microenvironment." (PMID 35897832, 2022). "Indeed, we have proved that the intracellular protein influences in vitro tumor development and growth by spheroids analysis, in addition to defining the modification about cell protein pattern in ANXA1 KO model compared to the WT one." (PMID 36230687, 2022). "We found CAFs which highly expressed CTHRC1 (from F04 and F08) and tumor associated macrophages were mediated by a different set of ligand-receptor pairs, including THY1/aXb2 complex, GRN/TNFRSF1A, CD99/PILRA, CD74/MIF, APP/CD74, ANXA1/FPR1, etc." (PMID 35928443, 2022). "Moreover, ANXA1 can act either as an anti-tumor or as a pro-tumor factor, depending on cellular localization, tumor type and stage, as well as on its expression levels." (PMID 36230687, 2022). "As the progression of metastasis requires collusion between cancer cells and localized accumulations of myeloid cells, the findings in this study advocate that ANXA1 in the tumor microenvironment is partially responsible for recruitment of infiltrating microglia through activation of FPR1 and FPR2." (PMID 35382852, 2022). "We also investigated how ANXA1 action could influence the PC pharmacological response both in basal conditions and by mimicking a tumor system through the addition of autocrine EVs." (PMID 36230687, 2022). "Notably, several genes related to matrix composition and immune cell recruitment were upregulated in squamous cells (Anxa1, Ecm1, Il1rn, Itgb4), as well as genes that are reported to be tumor suppressors (Serpin5b, Phlda3)." (PMID 35600339, 2022).
tumor (continued). "Annexin A1 (ANXA1) expression is associated with EMT; multiple malignant pathways; and the infiltration of fibroblasts, keratinocytes, and T-helper type 2 cells in the tumor microenvironment." (PMID 33804148, 2021). "However, AnxA1 can act either as an anti-tumor or as a pro-tumoral factor, depending on the tumor origin and stage." (PMID 34571894, 2021). "Thus, Gege3 has turned out as an interfering element in a finely regulated cross-talk among PC cells and the tumor microenvironment in which one of the major actors is represented by ANXA1 protein." (PMID 34944403, 2021). "For these reasons, in this review we aim to describe the role of Annexin A1 in the establishment of the tumor microenvironment, focusing on the immunosuppressive and immunomodulatory activities of Annexin A1 and on its interaction with the epidermal growth factor receptor." (PMID 34571894, 2021). "Moreover, compared with ductal-normal and ductal-tumor cells, CD55_ADGRE5, CD99_PILRA, ANXA1_FPR3 interactions were drastically upregulated in the malignant cells." (PMID 35087839, 2021). "Alternatively, increased binding of AnxA1 released from cancer cells to FPR2 on regulatory T cells may impede anti-tumour immune responses." (PMID 33810523, 2021). "ANXA1 may act as a tumor inhibitor in the early stage of cancer, but in the late stage of cancer, it may play the opposite role." (PMID 34512870, 2021). "The association between ANXA1 and the tumor immune microenvironment in PC has not been fully studied." (PMID 33804148, 2021). "The result showed that NXA1 expression was positively correlated with CD274 and CD276 expression, which indicated ANXA1 could influenced the tumor microenvironment by regulating these tumor immune genes." (PMID 34422796, 2021). "Furthermore, we investigated the molecular function of ANXA1 in tumor cell proliferation and migration." (PMID 33959206, 2021). "Likewise, coupling anticancer drugs to a peptide that recognizes AnxA1 on the tumour vasculature surface enabled drug delivery across the blood–brain barrier to suppress growth of brain tumours." (PMID 33810523, 2021). "Further studies are needed to examine the correlation of tumor ANXA1 expression with serum level." (PMID 33597040, 2021). "The in vivo data displayed that silencing of ANXA1 retarded the tumor growth of PTC cells." (PMID 33531975, 2021). "One of the first studies aimed to assess the effects of pharmacological treatments for cancer therapy by using an on chip approach is represented by a study addressing the role of formyl peptide receptor 1 (FPR1)/annexin a1 (Anxa1) axis in anti-tumor response to anthracycline-based chemotherapy." (PMID 33842539, 2021). "ANXA1 (annexin A1), known as an endogenous anti-inflammatory protein, has now been recognized to be closely related to tumor cell proliferation, invasion, differentiation, apoptosis, metastasis and chemotherapy sensitivity via modulation of various cancer-associated pathways." (PMID 33597040, 2021). "Interestingly, Anxa1 expression in the tumor cell cytoplasm in IF7-10B drug-mediated BNCT groups remarkably increased relative to that seen in non-irradiated groups." (PMID 33446132, 2021). "Our finding that Gege3 is able to inhibit these induced effects of the extracellular form of ANXA1 suggested that this molecule could significantly interfere with the cross-talk that ANXA1 performs in the tumor microenvironment to promote PC progression." (PMID 34944403, 2021). "Although we did not observe a significant difference in the number of CD31-positive blood vessels per tumor area between groups, IF7-10B drug-mediated BNCT may destroy Anxa1-positive tumor vasculature as a way of boosting BNCT therapeutic potential." (PMID 33446132, 2021). "In tumorigenesis, the expression of ANXA1 was found to be highly tissue and tumor specific." (PMID 33959206, 2021). "In conclusion, ANXA1 expression might elongate patients' survival by inhibiting tumor cell migration and subsequent metastasis." (PMID 33959206, 2021).